FUNDC1 (FUN14 domain containing 1)
Diseases named in the same sentence as FUNDC1 in open-access papers (continued):
Sharing a sentence is not in itself a finding about the gene and the disease.
Sepsis (8 papers, 2021 to 2026). Sepsis is defined as life-threatening organ dysfunction caused by a dysregulated host response to infection. "To elucidate the mechanisms underlying emodin's protective effects in sepsis, we investigated its role in regulating FUNDC1-mediated mitophagy in the lungs of septic mice." (PMID 40520006, 2025). "Our research demonstrates that the protective effect of FGF2 on mitophagy in septic cardiomyopathy is mediated by FUNDC1, providing novel insight into the underlying mechanisms of sepsis-induced cardiac dysfunction." (PMID 41292702, 2025). "Activation of FUNDC1-associated mitotic phagocytosis was shown to protect the heart against lipopolysaccharides (LPS)-induced sepsis through preserving mitochondrial function and structure." (PMID 35645834, 2022). "In vivo, emodin confers significant protection in sepsis models, with these protective effects being lost in NLRP3-deficient mice or upon macrophage-specific deletion of FUNDC1." (PMID 40520006, 2025). "Taken together, these results demonstrate that emodin protects against LPS-induced sepsis by promoting FUNDC1-dependent mitophagy, thereby suppressing NLRP3 inflammasome activation and mitigating the ensuing inflammatory response in mice." (PMID 40520006, 2025). "Based on this finding, targeting FUNDC1-dependent mitotic phagocytosis should be a potential strategy for reconciliation of cardiac dysfunction in sepsis." (PMID 35645834, 2022). "A study reported that the inhalation of H2 gas promoted mitophagy through the regulation of FUNDC1-dependent manner and protected mice from the sepsis-induced liver injury." (PMID 34164394, 2021). "The protective effect of H2 on liver injury in sepsis could be effectively reversed by the FUNDC1 inhibitor." (PMID 34164394, 2021). "It has been shown that H2 could further enhance sepsis-induced elevation of FUNDC1 expression, and the FUNDC1 inhibitor peptide P could effectively reverse the protective effect of H2, indicating the involvement of FUNDC1 in the stimulation of mitophagy by H2." (PMID 38020926, 2023). "Our study has now revealed that FGF2 regulates FUNDC1-related mitophagy via the AMPK pathway in the context of septic cardiomyopathy, providing a novel insight into the pathophysiology of sepsis-induced cardiac dysfunction." (PMID 41292702, 2025). "Together, FUNDC1-dependent MAMs is important in LPS-induced sepsis and IL-6/STAT3 inhibitor might improve cardiac dysfunction through regulating the FUNDC1-dependent MAMs formation." (PMID 35118141, 2021).
cardiac hypertrophy (5 papers, 2020 to 2025). "Thus, the evidence indicates that FUNDC1-mediated mitophagy is involved in cardiac hypertrophy and that interference with the associated signaling pathways could prevent the progression or deterioration of the disease." (PMID 35096821, 2021). "In mice with cardiac hypertrophy induced by isoproterenol injection for 15 days, baicalein upregulated the mitophagy receptor FUN14 domain containing 1 (FUNDC1) and upregulated autophagy." (PMID 37728583, 2024). "Different expression levels of FUNDC1 and its phosphorylated state at different sites alleviate or exacerbate hypoxia and ischemia/reperfusion injury, cardiac hypertrophy, or metabolic damage through promotion or inhibition of mitophagy." (PMID 35096821, 2021). "FUNDC1-dependent mitophagy has also been shown to play a critical role in cardiac hypertrophy." (PMID 35096821, 2021).
Cerebral ischemia (4 papers, 2016 to 2024). Restriction of arterial blood supply to the brain associated with insufficient oxygenation to support the metabolic requirements of the tissue. "Recent studies have demonstrated the beneficial properties of FUNDC1-mediated mitophagy in cardiac and cerebral ischemia-reperfusion injuries." (PMID 36425056, 2022). "Some studies documented that FUNDC1-mediated mitophagy could improve cerebral ischemia via inhibiting NLRP3 inflammasome." (PMID 35959490, 2022). "What are the roles of PINK1 and FUNDC1 in the process of cerebral ischemia?" (PMID 27554669, 2016).
ischemic stroke (4 papers, 2023 to 2026). A stroke disorder caused by obstruction of blood flow to the brain, due to thrombotic (local blood clot formation) or embolic (due to a blood clot or other material traveling from another site) event. "In summary, the neuroprotective effect of EA against ischemic stroke might be achieved by inhibiting neuronal apoptosis through PGAM5/FUNDC1-dependent mitophagy." (PMID 41933402, 2026). "In ischemic stroke, mitophagy could be predominantly mediated by the PINK1/Parkin pathway, Bcl-2/E1B-19 KD-interacting protein 3 (BNIP3), NIP3-like protein X (NIX, also known as BNIP3L), and FUN14 domain containing 1 (FUNDC1)." (PMID 37033646, 2023).
laryngeal carcinoma (4 papers, 2021 to 2024). Carcinoma that arises from the laryngeal epithelium. "Studies have shown that hydrogen peroxide exposure in laryngeal cancer cells elevates FUNDC1 levels." (PMID 39596452, 2024). "This upregulation of FUNDC1 enhances mitophagy, enabling laryngeal cancer cells to better withstand oxidative stress." (PMID 39596452, 2024). "In addition, FUNDC1-mediated mitophagy protects laryngeal cancer cells against oxidative stress while FUNDC1 knockout in the liver initiates liver cancer by activating inflammation." (PMID 34699308, 2022). "In addition to FUNDC1, which mediates oxidative stress-induced mitophagy in laryngeal cancer cells, BNIP3 is also involved in the regulation of mitophagy in cancer cells." (PMID 33879840, 2021). "In addition, some studies have found that hydrogen peroxide can up-regulate the expression of FUNDC1 by activating the ERK1/2 signaling, triggering mitochondrial autophagy, making laryngeal cancer cells more suitable for survival." (PMID 35134750, 2022).
lung carcinoma (4 papers, 2019 to 2024). "This aligns with our findings, as our results show that FUNDC1-mediated receptor-independent mitophagy may be an important pathway through which SA regulates mitochondrial homeostasis in lung cancer cells." (PMID 39430236, 2024). "In addition, studies have revealed elevated expression levels of FUNDC1 in lung cancer tissues, which aligns with our findings." (PMID 38155968, 2023).
renal fibrosis (4 papers, 2021 to 2025). A final common manifestation of a wide variety of chronic kidney diseases characterized by glomerulosclerosis and tubulointerstitial fibrosis. "Masson’s trichrome staining of the renal sections from UUO-Fundc1-/- mice revealed more positive blue staining of collagenous fibers, indicating that renal fibrosis was exacerbated with Fundc1 ablation." (PMID 33942716, 2021). "PAA can promote mitochondrial autophagy by downregulating FUNDC1, thereby having a beneficial effect on podocyte damage in DKD renal fibrosis." (PMID 39619610, 2024). "We will discuss the role of FUNDC1 in acute kidney injury (AKI), cardiorenal syndrome (CRS), diabetic nephropathy (DN), chronic kidney disease (CKD), renal fibrosis (RF) and renal anemia, aiming to provide new ideas and strategies for the treatment of kidney diseases." (PMID 39445333, 2024).
acute kidney injury (3 papers, 2021 to 2024). Sudden and sustained deterioration of the kidney function characterized by decreased glomerular filtration rate, increased serum creatinine or oliguria. "For example, during this study, it was reported that FUNDC1-dependent mitophagy in tubule cells plays protective roles in ischemic acute kidney injury." (PMID 33942716, 2021).
Alzheimer disease (3 papers, 2024 to 2025). A progressive, neurodegenerative disease characterized by loss of function and death of nerve cells in several areas of the brain leading to loss of cognitive function such as memory and language. "Emerging evidence implicates FUNDC1 dysregulation in neurodegenerative diseases, particularly Alzheimer’s disease (AD), where defective mitophagy exacerbates hallmark pathologies including Aβ plaque deposition and hyperphosphorylated Tau-driven neurofibrillary tangles." (PMID 40421101, 2025). "It provides a focused analysis of the specific functions and activation mechanisms of key receptors—including BNIP3, NIX, FUNDC1, and AMBRA1—in models of Alzheimer’s disease, Parkinson’s disease, and amyotrophic lateral sclerosis." (PMID 41341510, 2025).
chronic obstructive pulmonary disease (3 papers, 2022). A chronic and progressive lung disorder characterized by the loss of elasticity of the bronchial tree and the air sacs, destruction of the air sacs wall, thickening of the bronchial wall, and mucous accumulation in the bronchial tree. "Increasing evidence suggests that the pathogenesis of chronic obstructive pulmonary disease (COPD) is associated with FUN14 domain protein 1 (FUNDC1)-mediated mitophagy." (PMID 35134750, 2022). "Silencing FUNDC1 attenuates chronic obstructive pulmonary disease by inhibiting mitochondrial autophagy." (PMID 34699308, 2022).
diabetic cardiomyopathy (3 papers, 2022 to 2024). Diabetic cardiomyopathy is a disorder of the heart muscle in people with diabetes. "Research has shown that AMPK activation-mediated inhibition of FUNDC1 is an effective approach to treating diabetic cardiomyopathy, confirming FUNDC1 as a downstream target of AMPK." (PMID 39506876, 2024). "Studies has revealed that high glucose-induced AMPK inhibition contributes to the onset of diabetic cardiomyopathy by upregulation of FUNDC1, FUNDC1-governed MAMs, and rises in mitochondrial Ca2+ in the heart." (PMID 35645834, 2022). "Interestingly, downregulation of FUNDC1 loosened FUNDC1-governed MAMs to reverse diabetic cardiomyopathy through inhibition of mitochondrial Ca2+ overload and mitochondrial injury." (PMID 35645834, 2022).
glioblastoma (3 papers, 2021 to 2025). The most malignant astrocytic tumor (WHO grade IV). "They demonstrated the role of FUNDC1 in prostate adenocarcinoma, glioblastoma, lung adenocarcinoma, and breast adenocarcinoma." (PMID 34272359, 2021).
Hepatic steatosis (3 papers, 2019 to 2025). Steatosis is a term used to denote lipid accumulation within hepatocytes. "This is in line with the fact that FUNDC1 removal nullified CK2α knockout‐elicited benefit against HFD‐evoked hepatic steatosis and injury." (PMID 40656543, 2025). "Schematic graph exhibiting possible mechanism(s) for the role of CK2α and FUNDC1 in high fat diet‐induced hepatic steatosis." (PMID 40656543, 2025).
liver cancer (3 papers, 2019 to 2022). An epithelial or non-epithelial malignant neoplasm that arises from the liver. "Compared with a low expression level, a high expression level of FUNDC1 correlated with a better prognosis in lung, ovarian, kidney, and thyroid cancers and a poorer prognosis in brain, skin, and liver cancers." (PMID 31998650, 2019).
Parkinson disease (3 papers, 2021 to 2025). A progressive degenerative disorder of the central nervous system characterized by loss of dopamine producing neurons in the substantia nigra and the presence of Lewy bodies in the substantia nigra and locus coeruleus. "The PINK1/Parkin mitophagy pathway, as well as alternative mitophagy pathways controlled by BNIP3L/Nix and FUNDC1, are emerging targets to enhance mitophagy to treat Parkinson's disease." (PMID 35311891, 2022).
Stroke (3 papers, 2018 to 2024). Sudden impairment of blood flow to a part of the brain due to occlusion or rupture of an artery to the brain. "In addition to the canonical mitophagy pathway, under hypoxic conditions induced by stroke, the reduction of hydroxylated hypoxia-inducible factor (HIF) accelerates HIF accumulation, enhancing mitophagy sensitivity by activating FUNDC-1, Bnip-3, and NIX." (PMID 39594471, 2024). "Although both FUNDC-1 and Bnip-3 are involved in mitophagy induction, FUNDC-1 does not appear to influence neuronal mitophagy as extensively as Bnip-3, which contributes to the sequestration of mitochondria into autophagosomes, thereby triggering delayed neuronal death in stroke." (PMID 39594471, 2024). "Mechanisms linking FUNDC1 to mitophagy have emerged as a novel research direction for various kinds of disease, but the molecular mechanism of FUNDC1-mediated mitophagy in the pathologies of stroke has not been reported so far." (PMID 30501621, 2018).
allergic rhinitis (2 papers, 2025). Inflammation of the nasal mucous membranes caused by an IgE-mediated response to external allergens. "Ginsenoside Rh1 is involved in the inflammatory process of allergic rhinitis through the AMPK/ULK1/FUNDC1 signaling axis." (PMID 40535916, 2025). "In allergic rhinitis models, Rh1’s therapeutic efficacy operates through activation of the AMPK/ULK1/FUNDC1 pathway, which mediates mitochondrial autophagy and subsequently reduces NLRP3 inflammasome activation while restoring Th1/Th2 balance." (PMID 41155644, 2025).
brain injury (2 papers, 2024 to 2025). Acute and chronic (see also brain INJURIES, CHRONIC) injuries to the brain, including the cerebral hemispheres, CEREBELLUM, and brain STEM. "The involvement of PHLDA1 in mitophagy mediated by FUN14 Domain-Containing Protein 1 (FUNDC1) in ischemic brain injury has recently been reported." (PMID 39630301, 2025).
colorectal cancer (2 papers, 2019 to 2025). A primary or metastatic malignant neoplasm that affects the colon or rectum. "In addition, for colorectal cancer, FUNDC1 only had a protective effect on RFS for rectum adenocarcinoma (READ) (OS: HR = 2.01, 95% CI from 0.6 to 6.7, logrank P = 0.25; RFS: HR = 0.18, 95% CI from 0.03 to 1.04, logrank P = 0.033)." (PMID 31998650, 2019). "However, the role of FUNDC1-mediated mitophagy in colorectal cancer has not yet been fully elucidated." (PMID 41315223, 2025).
glioma (2 papers, 2019 to 2022). A benign or malignant brain and spinal cord tumor that arises from glial cells (astrocytes, oligodendrocytes, ependymal cells). "Whereas, we found a significant decrease of BNIP3L/NIX and HIF-1α in C6-glioma and N2a cells after treatment with Cur and or SLCP, whereas no significant changes were observed in the case of FUNDC1 protein in both the cell lines." (PMID 30669284, 2019).
Hepatic fibrosis (2 papers, 2024). The presence of excessive fibrous connective tissue in the liver. "Recent data showed that FUNDC1-mediated mitophagy led to ferroptosis and hepatic fibrosis by degrading glutathione peroxidase 4 (GPX4) in mitochondria, while knockdown of FUNDC1 ameliorated fibrosis." (PMID 39183973, 2024).
infarct (2 papers, 2022). "Further studies showed that HA increased the expression of Fundc1 protein and its associated mitophagy protein LC3 in myocardial tissue after infarction." (PMID 35422895, 2022).
intracerebral hemorrhage (2 papers, 2023 to 2024). A cerebrovascular disorder characterized by bleeding into one or both cerebral hemispheres including the basal ganglia and the cerebral cortex. "Another example is that FUNDC1 alleviates inflammation after intracerebral hemorrhage (ICH) by inducing mitophagy in mice, indicating FUNDC1 may be a potential target for ICH treatment." (PMID 36846712, 2023).
left ventricular hypertrophy (2 papers, 2021 to 2022). Enlargement of the LEFT VENTRICLE of the heart. "Additionally, antioxidant supplementation with alpha-lipoic acid (α-LA) protects mice from TAC-induced left ventricular hypertrophy through the upregulation of FUN14 domain-containing protein 1 (FUNDC1), a mitochondrial membrane receptor that promotes mitophagy." (PMID 36187489, 2022).
leukemia (2 papers, 2019 to 2024). A malignant (clonal) hematologic disorder, involving hematopoietic stem cells and characterized by the presence of primitive or atypical myeloid or lymphoid cells in the bone marrow and the blood. "By inducing FBXL2, FUNDC1 reduces ferroptosis in leukemia through the inhibition of mitochondrial damage." (PMID 38947217, 2024). "The mRNA expression levels of FUNDC1 were found to be up-regulated in serum samples from CL patients as well as in leukemia cell lines." (PMID 38947217, 2024). "The results revealed that compared with that in the respective normal groups, FUNDC1 expression was higher in cancer groups, including breast, cervical, colorectal, lung, ovarian, pancreatic, and prostate cancers as well as leukemia and lymphoma." (PMID 31998650, 2019). "The up-regulation of FUNDC1 was found to promote leukemia metastasis." (PMID 38947217, 2024). "In a leukemia model, FUNDC1 up-regulation induces the expression of FBXL2." (PMID 38947217, 2024). "Moreover, FUNDC1 up-regulation reduces FBXL2 ubiquitination, thus maintaining FBXL2 protein expression in leukemia." (PMID 38947217, 2024).
nasal polyps (2 papers, 2022 to 2025). "The expression of PINK1, BNIP3, and FUNDC1 proteins was also decreased in the nasal polyps of patients with noeCRSwNP." (PMID 35747690, 2022). "Western blot analysis of mitochondrial proteins also revealed significantly reduced levels of PINK1, parkin, BNIP3, and FUNDC1 in the nasal polyps of patients with eCRSwNP (P < 0.001, 0.004, 0.002, and 0.013, respectively), compared with control tissues." (PMID 35747690, 2022). "Beclin 1, PINK1, BNIP3, and FUNDC1 levels were significantly reduced in the nasal polyps of patients with eCRSwNP or noeCRSwNP." (PMID 35747690, 2022). "In this study, we demonstrated that the expression of PINK1, parkin, BNIP3, and FUNDC1 proteins was markedly decreased in the nasal polyps of patients with eCRSwNP, compared with control tissues." (PMID 35747690, 2022). "Western blot analysis of total proteins revealed reduced levels of PINK1, parkin, BNIP3, and FUNDC1 in the nasal polyps of patients with eCRSwNP (P = 0.002, <0.001, 0.001, and <0.001, respectively) or noeCRSwNP (P = 0.002, <0.001, <0.001, and <0.001, respectively), compared with control tissues." (PMID 35747690, 2022). "Although mitophagy-related proteins such as PINK1, BNIP3, and FUNDC1 typically exhibit compensatory up-regulation in various pathologies, their expression is significantly reduced in nasal polyp tissues of asthma patients with chronic rhinosinusitis with nasal polyps (CRSwNP)." (PMID 41026942, 2025).
non-small cell lung carcinoma (2 papers, 2018 to 2026). A group of at least three distinct histological types of lung cancer, including non-small cell squamous cell carcinoma, adenocarcinoma, and large cell carcinoma. "Here, we uncover FUNDC1-dependent mitophagy as a key protective mechanism in EGFR-mutant non-small cell lung cancer (NSCLC)." (PMID 42152723, 2026). "Moreover, studies on the PGAM5/FUNDC1/BCL-xL/DRP1 axis described previously in non-small cell lung cancer points toward the direction that targeting mitophagy through FUNDC1 in combination with X-ray irradiation could improve treatment of this type of human cancer." (PMID 30250843, 2018).
ovarian carcinoma (2 papers, 2019 to 2022). A malignant neoplasm originating from the surface ovarian epithelium. "Meanwhile, FUNDC1 had a protective role in the other 3 cancer types, including bladder (DSS: total number = 165, HR = 0.54, Cox P = 0.002943), lung (OS: total number = 204, HR = 0.48, Cox P = 0.036986), and ovarian cancers (DFS: total number = 185, HR = 0.38, Cox P = 0.044859)." (PMID 31998650, 2019).